DPM1 (dolichyl-phosphate mannosyltransferase subunit 1, catalytic)
Description:
Transfers mannose from GDP-mannose to dolichol monophosphate to form dolichol phosphate mannose (Dol-P-Man) which is the mannosyl donor in pathways leading to N-glycosylation, glycosyl phosphatidylinositol membrane anchoring, and O-mannosylation of proteins; catalytic subunit of the dolichol-phosphate mannose (DPM) synthase complex.
Synonyms: MPDS; CDGIE
Tractability: PROTAC: ubiquitination databases record sites on it; its protein half-life has been measured.
Target class: Enzyme; Transferase
Gene: Protein-coding gene on chromosome 20 (50,934,852 to 50,959,140, reverse strand). Ensembl gene ENSG00000000419.
Subcellular location: Endoplasmic reticulum
Pathways (Reactome):
Disease: Defective DPM1 causes DPM1-CDG; Defective DPM2 causes DPM2-CDG; Defective DPM3 causes DPM3-CDG; Maturation of DENV proteins
Metabolism of proteins: Synthesis of dolichyl-phosphate mannose
Gene Ontology:
Molecular function: dolichyl-phosphate beta-D-mannosyltransferase activity; protein binding; metal ion binding
Biological process: dolichol phosphate mannose biosynthetic process; dolichyl monophosphate biosynthetic process; GPI anchor biosynthetic process; protein O-linked glycosylation via mannose; dolichol-linked oligosaccharide biosynthetic process
Cellular component: dolichol-phosphate-mannose synthase complex; endoplasmic reticulum; endoplasmic reticulum membrane; membrane; nucleus
Genetic constraint (gnomAD): Loss-of-function variants: 20 observed, 28.92 expected, observed/expected ratio (o/e) 0.69, 90% interval 0.49 to 1. The upper end of that interval is the gene's LOEUF score, 1, which puts it in group 4 of 6, group 1 being the genes least tolerant of losing a copy. Missense variants: 243 observed, 257.8 expected, observed/expected ratio (o/e) 0.94, 90% interval 0.85 to 1.05. Synonymous variants: 99 observed, 88.53 expected, observed/expected ratio (o/e) 1.12, 90% interval 0.95 to 1.32.
Gene-disease validity (ClinGen):
ClinGen rates the evidence that DPM1 causes each of these diseases.
congenital disorder of glycosylation type 1E (autosomal recessive): Definitive.
Homologues: Orthologues: chimpanzee DPM1 (99% identical), macaque DPM1 (97% identical), dog DPM1 (97% identical), pig DPM1 (94% identical), rabbit DPM1 (93% identical), guinea pig DPM1 (92% identical), mouse Dpm1 (91% identical), rat Dpm1 (91% identical), tropical clawed frog dpm1 (81% identical), zebrafish dpm1 (81% identical), Drosophila melanogaster Dpm1 (68% identical), Caenorhabditis elegans dpm-1 (59% identical). Paralogues in human: ALG5 (25% identical).
Diseases named in the same sentence as DPM1 in open-access papers:
DPM1 is named in the same sentence as 37 diseases in open-access papers, as found by Europe PMC text mining. Sharing a sentence is not in itself a finding about the gene and the disease. The quoted sentences say what the papers report.
pancreatic cancer (5 papers, 2015 to 2025). "mRNA biomarkers (KRAS, MBD3L2, ACRV1, DPM1) can differentiate pancreatic cancer patients from healthy individuals." (PMID 39958008, 2025). "Studies have identified KRAS, MBD3L2, ACRV1, and DPM1 as biomarkers in salivary mRNA to detect pancreatic cancer with high specificity." (PMID 38202898, 2023).
breast carcinoma (3 papers, 2022 to 2025). "Moreover, DPM1 is upregulated in several cancers, including hepatocellular carcinoma and breast cancer, where it correlates with tumor progression, poor prognosis, and subtype-specific glycosylation features, particularly in luminal breast cancer." (PMID 41061966, 2025). "The DPM1 gene plays a crucial role in colorectal cancer and breast cancer, but its expression measured by means of the microarray analysis in tissue samples obtained from patients with breast cancer showed significant differences in values ranging from 761 up to even 5424." (PMID 35326572, 2022).
hepatocellular carcinoma (3 papers, 2020 to 2025). A malignant tumor that arises from hepatocytes. "The transcriptional and proteinic expressions of DPM1/2/3 were both over-expressed in patients with hepatocellular carcinoma." (PMID 33282554, 2020). "We also performed quantitative real-time PCR experiments in human normal hepatocytes and hepatoma cells to verify the expressions of DPM1/2/3 and results showed that the expression of DPM1 was significantly increased in hepatoma cells SMMC-7721 and HepG2." (PMID 33282554, 2020). "It is worth noting that DPM1 is known to promote tumor progression and may serve as a prognostic biomarker in hepatocellular carcinoma." (PMID 41061966, 2025). "Taken together, these results suggested that DPM1 could be a potential prognostic biomarker for survivals of hepatocellular carcinoma patients." (PMID 33282554, 2020). "Also, and at variance with DPM2 and 3, the DPM1 mRNA was upregulated (by 1.50-fold) in the Hep G2 hepatic cancer cell line, which suggests that DPM1 could be a potential biomarker with survival prognostic value in patients with hepatocellular carcinoma." (PMID 36494657, 2022). "We evaluated DPM1, DPM2 and DPM3 expression levels in a panel of three cell lines: two hepatoma cells (HepG2 and SMMC-7721) and one normal liver cell line (QSG-7701)." (PMID 33282554, 2020).
liver cancer (3 papers, 2020 to 2022). An epithelial or non-epithelial malignant neoplasm that arises from the liver. "Besides, higher mRNA expressions of DPM1/2/3 were significantly associated with shorter OS in liver cancers patients." (PMID 33282554, 2020). "Coherently with results reported in patients with liver cancer, DPM1, 2 and 3 genes are overexpressed (by 4.00-, 1.51- and 1.47-fold), at the mRNA level in the SMMC-7721 cell line." (PMID 36494657, 2022). "We detected that liver cancer patients with low transcriptional levels of DPM1 (p = 0.007), DPM2 (p = 0.0032) and DPM3 (p = 0.029), were significantly connected with longer OS." (PMID 33282554, 2020). "The combined application of DPM1 and other already-existed biomarkers would greatly improve the early diagnosis and accurate prognosis of liver cancers." (PMID 33282554, 2020). "In addition, higher mRNA expressions of DPM1/2/3 were found to be significantly related to shorter overall survival in liver cancer patients." (PMID 33282554, 2020). "DPM1 was the most potential prognostic biomarker for liver cancer via cell experiment verified." (PMID 33282554, 2020). "Moreover, high genetic alteration rate of DPM1/2/3 (41%) was also observed, and genetic alteration in DPM1/2/3 was associated with shorter OS in HCC patients, which provide a better understanding of molecular targets for improved liver cancer therapeutic strategies in the future." (PMID 33282554, 2020). "Therefore, it is possible to use DPM1 as an effective supplemental biomarker of liver cancer." (PMID 33282554, 2020). "B4GALT2, B4GALT3, DPM1, DPM2, HS2ST1, and PIGS are unfavorable prognostic markers in liver cancer according to the analysis by human protein atlas." (PMID 32850363, 2020).
melanoma (2 papers, 2022 to 2024). A malignant, usually aggressive tumor composed of atypical, neoplastic melanocytes. "These include a previously undocumented exon of gene TUFM (AltAnalyze: I8.1_28843525-E9.1) that is highly specific to melanoma patients (BayesTS score = 0.029), whereas an exon-skipping event DPM1 (E6.1–E8.2) is broadly present in healthy tissues (BayesTS score = 0.864)." (PMID 39515334, 2024). "We observed a significant reduction in both GFAT-1 and DPM1 expressions in metastatic melanoma cells treated with anandamide, which may suggest that the biosynthesis of glycans in these cells was downregulated." (PMID 35326572, 2022). "The mRNA expression of two glycosyltransferases (glutamine fructose-6-phosphate aminotransferase 1, GFAT-1; and dolichyl-phosphate mannosyltransferase subunit 1, DPM1) in melanoma cells incubated with 1 μM AEA were investigated by means of the RT-qPCR analysis." (PMID 35326572, 2022).
muscular dystrophy (2 papers, 2019 to 2023). Muscular dystrophy (MD) refers to a group of more than 30 genetic diseases characterized by progressive weakness and degeneration of the skeletal muscles that control movement. "Deficiency in DPM1 has been associated with CDG syndrome due to deficient protein N-glycosylation, whereas defect in DPM3 causes a muscular dystrophy associated with abnormal O-mannosylation of dystroglycan." (PMID 37152991, 2023). "DOLK‐CDG, DPM1‐CDG, DPM2‐CDG, and DPM3‐CDG are defects in the DPM synthesis showing both CDG‐I abnormalities and reduced O‐mannosylation of alpha‐dystroglycan (αDG), which leads to muscular dystrophy‐dystroglycanopathy." (PMID 31741824, 2019).
buphthalmia (1 paper, 2022). "Eyes abnormalities such as glaucoma and buphthalmia were present in SRD5A3 patients, and optic nerve/disc alterations are a relatively nonspecific finding, present in ALG6‐, DPM1‐, MPDU‐, and SRD5A3‐CDG." (PMID 35279850, 2022).
cholangiocarcinoma (1 paper, 2025). A carcinoma that arises from the intrahepatic biliary tree (intrahepatic cholangiocarcinoma) or from the junction, or adjacent to the junction, of the right and left hepatic ducts (hilar cholangiocarcinoma). "Collectively, these findings highlight DPM1 as a clinically relevant regulator of tumor immune escape, with potential as both a predictive biomarker and therapeutic target to improve immunotherapy outcomes in cholangiocarcinoma." (PMID 41061966, 2025).
congenital disorder of glycosylation (1 paper, 2017). Congenital disorder of glycosylation (CDG) is a fast growing group of inborn errors of metabolism characterized by defective activity of enzymes that participate in glycosylation (modification of proteins and other macromolecules by adding and processing of oligosaccharide side chains). "Failure to produce or utilize Dol-P-Man compromises organism viability, and in humans, several mutations in the human dpm1 gene lead to congenital disorders of glycosylation (CDG)." (PMID 28743912, 2017).
dystroglycanopathy (1 paper, 2022). "Pathogenic variants in DPM1 and DPM2 are associated with muscle–eye–brain (MEB) disease, whereas DPM3 variants have mostly been reported in patients with isolated muscle disease—dystroglycanopathy." (PMID 35932216, 2022).
gastroesophageal reflux (1 paper, 2022). "Dysphagia and/or gastroesophageal reflux was present in ALG1‐, ALG6‐, ALG11‐, ALG12‐, DPM1‐, and DOLK‐CDG." (PMID 35279850, 2022).
liver cirrhosis (1 paper, 2020). "The relationships between the expressions of DPM1/2/3 and CLD including HBV-related liver cirrhosis, HCV-related liver cirrhosis and non-alcoholic steatohepatitis were also analyzed." (PMID 33282554, 2020). "We found that the expressions of DPM1/2/3 in HBV and HCV-related liver cirrhosis and non-alcoholic steatohepatitis samples were more or less higher than normal samples." (PMID 33282554, 2020).
lymphoma (1 paper, 2010). A malignant (clonal) proliferation of B- lymphocytes or T- lymphocytes which involves the lymph nodes, bone marrow and/or extranodal sites. "In order to evaluate fOSGN2-P generation in lymphoblastoid cells incapable of generating mature DLO, the DPM synthase deficient (null mutation in mouse DPM1 gene) mouse lymphoma cell line Thy-1 along with its parental cell line (BW5147.3) were examined." (PMID 20652024, 2010). "To conclude, our results show that in EBV lymphoblastoid cells from normal subjects and mouse lymphoma cells fOSGN2-P generation occurs at low levels, but in EBV CDG I cells and DPM1-deficient mouse lympoma cells increases in immature DLO intermediates lead to increases in fOSGN2-P generation." (PMID 20652024, 2010).
cancer (5 papers, 2015 to 2025). A tumor composed of atypical neoplastic, often pleomorphic cells that invade other tissues. "Our results showed that over-expressions of DPM1/2/3 were significantly associated with clinical cancer stages and pathological tumor grades in HCC patients." (PMID 33282554, 2020). "DPM1 catalyzes the first committed step in the N-glycosylation pathway and is also amplified in cancer." (PMID 40789468, 2025). "In order to explore the gene expressions of three subunits of DPMS in different types of cancer, mRNA expressions of DPM1, DPM2 and DPM3 were analyzed by UALCAN." (PMID 33282554, 2020). "However, the degree of staining in DPM1, B4GALT3, B4GALT2, and B4GALNT1 was stronger in cancer tissues than normal tissues." (PMID 35356430, 2022).
tumor (5 papers, 2016 to 2025). "To assess potential immunological implications, we correlated the tumor-upregulated, DPM1-associated glycopeptides with tumor-infiltrating immune cell populations." (PMID 41061966, 2025). "One of the key findings of this study is the identification of DPM1 as a central glycosylation enzyme associated with tumor-specific glycopeptides and reduced immune cell infiltration in extrahepatic cholangiocarcinoma (eCCA)." (PMID 41061966, 2025). "Integration of glycopeptide–DPM1 correlation data with tumor-versus-adjacent tissue differential expression identified 23 glycopeptides that were both strongly associated with DPM1 expression and significantly upregulated in tumor tissues." (PMID 41061966, 2025). "In conclusion, our study provides a comparative analysis of N-glycosylation signatures between eCCA and iCCA and identifies DPM1 as a key regulator of tumor-associated glycopeptides and immune suppression in eCCA, offering new insights into its pathogenesis." (PMID 41061966, 2025). "DPM1, a glycosylation enzyme highly expressed in eCCA, was associated with tumor-specific N-glycopeptides and reduced immune cell infiltration." (PMID 41061966, 2025). "In the present study, we demonstrate that DPM1 is upregulated in eCCA and associated with altered glycosylation profiles that may contribute to an immunosuppressive tumor microenvironment." (PMID 41061966, 2025). "In addition, the expression of genes DPM1, 2 and 3, encoding the three subunits of dolichol-phosphate mannosyltransferase complex, has been found altered in several tumor types." (PMID 36494657, 2022). "Among them, DPM1, through its role in mannose donor biosynthesis, may indirectly modulate N-glycosylation patterns linked to an immunosuppressive tumor microenvironment, underscoring its involvement in eCCA pathogenesis and potential as a candidate for targeted therapy." (PMID 41061966, 2025). "To investigate the functional role of DPM1 in eCCA, we performed immunohistochemical staining on paired tumor and adjacent normal tissues." (PMID 41061966, 2025). "DPM1 expression was significantly elevated in tumor regions, as confirmed by increased positive staining area." (PMID 41061966, 2025). "The highest mRNA expressions of DPM1/2 were observed in tumor stage 3, while the maximum DPM3 mRNA expression was noticed in stage 4." (PMID 33282554, 2020). "In this paper, we studied the expressions of DPM1/2/3 in tumor cells and its relationship with tumorigenesis for the first time." (PMID 33282554, 2020). "DPM1, one of the relevant genes, is a vital sensor molecule related to the regulation of cytosolic Ca2+ levels in the maintenance of B-cell functions and a potential prognostic tumor marker of HCC." (PMID 35782861, 2022). "On the other hand, a series of other genes acting earlier in this pathway are overexpressed in tumor cells, namely DOLK, DPM1/2/3, POMGNT1, B3GALNT2, POMK and FKTN, hence exerting instead a pro-oncogenic role." (PMID 36494657, 2022). "The maximum mRNA expressions of DPM1/2 were showed in tumor grade 4, whereas the supreme mRNA expression of DPM3 was found in tumor grade 3." (PMID 33282554, 2020).
infection (1 paper, 2025). The state of being infected such as from the introduction of a foreign agent such as serum, vaccine, antigenic substance or organism. "Among the genes with the greatest positive effect on infection efficiency after knockout were multiple GPI biosynthesis genes: GPAA1, PIGA, PIGV, and DPM1 knockouts increased infection over 8-fold compared to control, while PIGO knockout increased infection approximately 4-fold." (PMID 40901862, 2025).
infectious disease (1 paper, 2025). A disorder directly resulting from the presence and activity of a microbial, viral, or parasitic agent in humans. "In infectious diseases, DPM1-mediated GPI biosynthesis contributes to immune evasion by supporting the synthesis of immunomodulatory glycolipids." (PMID 41061966, 2025).
DPM1 also shares sentences with these, for which no sentence is quoted: developmental delay (2 papers); epilepsy (2); head and neck squamous cell carcinoma (2); bladder cancer (1); chronic pancreatitis (1); colon adenocarcinoma (1); colorectal cancer (1); congenital disorder of glycosylation type 1E (1); congenital muscular dystrophy (1); disorder of glycosylation (1); epileptic encephalopathies (1); esophageal carcinoma (1); fructose intolerance (1); glaucoma (1); glioblastoma (1); microcephaly (1); non-alcoholic steatohepatitis (1); pancreatitis (1); rectum adenocarcinoma (1); Walker-Warburg syndrome (1).